MMP2 (matrix metallopeptidase 2)
Diseases named in the same sentence as MMP2 in open-access papers (continued):
Sharing a sentence is not in itself a finding about the gene and the disease.
cardiovascular diseases (54 papers, 2012 to 2025). "Recent studies have focused on the genetic variants of the MMP-2 gene, especially single nucleotide polymorphisms (SNPs), and their potential role in the development and progression of cardiovascular diseases." (PMID 40311090, 2025). "In obese individuals, an increased concentration of MMP-2 has been linked to cardiovascular disease, as it is potentially induced in the adipose tissue of obese individuals and contributes to the increase in extracellular collagen." (PMID 37372128, 2023). "There was a significant association between MMP-2 levels and cardiovascular disease with MMP-14 levels, which is a pro-MMP-2 activator." (PMID 37457745, 2023). "Age-dependent alterations in MMPs and TIMPs have been studied in skin and cardiovascular disease, and increased activities of MMP2 and MMP9 have been associated with tenocyte aging." (PMID 27391467, 2016). "A recent study showed that, after adjusting for age, sex, BMI, and cardiovascular disease, serum MMP-2 activity measured by gelatin zymography was associated with the AHI and oxygen desaturation index, which was defined as the frequency of oxygen desaturation drops by at least 3%." (PMID 40117070, 2025). "Genetic variants within the MMP-2 gene can significantly alter the risk of cardiovascular diseases." (PMID 40311090, 2025). "Therefore, we further tested the correlation between the relative levels of TIMP1, MMP2 and vWF (as assessed by slot blot) and several clinical/biochemical variables, and most common cardiovascular disease risk factors: age, BMI, or total cholesterol." (PMID 36362368, 2022). "MMPs are associated with cardiovascular diseases, in particular MMP-2 and MMP-9." (PMID 32545475, 2020). "In cardiovascular disease, sustained hyperactivity of MMP-2 and MMP-9 drives ECM degradation, maladaptive remodeling and ventricular dysfunction." (PMID 41154680, 2025). "The gelatinases MMP‐2 and MMP‐9 have a central role in cardiovascular disease; they are reportedly associated with heart tissue remodeling and were shown to be increased in the failing myocardium." (PMID 31932967, 2021). "Considering that DDR2 is present in the atherosclerotic plaques of humans and is associated with collagen Ι-induced secretion of MMP-2, the clinical role of DDR2 in cardiovascular disease should be elucidated in further experiments." (PMID 34956435, 2021). "MMP-2, also known as gelatinase A or type IV collagenase, plays a critical role in cardiovascular diseases and has emerged as a key enzyme involved in cardiac conditions associated with increased oxidative stress." (PMID 30571725, 2018). "Of all MMPs, MMP-2 (also known as gelatinase A or type IV collagenase) plays a critical role in cardiovascular diseases." (PMID 28286377, 2017). "Both MMP-2 and MMP-9 are involved in extracellular matrix remodeling, and have been implicated in increased susceptibility to cardiovascular diseases." (PMID 27295295, 2016). "We also examined cardiac mitochondrial preparations from a murine model of cardiovascular disease within a non-MMP-2 transgenic context." (PMID 22509276, 2012). "From this diverse group it has become increasingly evident that a specific metalloproteinase, MMP-2, is of central pathophysiologic and therapeutic importance in cardiovascular disease." (PMID 22509276, 2012). "It is known that the activation of extracellular MMPs plays an important role in the development and progression of various cardiovascular diseases and that oxidative stress is the main post-translational activating factor of MMP2 in the pathophysiology of systemic arterial hypertension." (PMID 39770106, 2024). "Also, cumulative evidence has suggested that autophagy plays an important role in the pathogenesis of cardiovascular diseases and tumors via the regulation of MMP-2 and MMP-9." (PMID 36211598, 2022). "Deep investigation of MMP2 in cardiovascular disease in patients with type 2 DM is required." (PMID 32455133, 2020).
cardiovascular diseases (continued). "Generally ROS has been shown to activate MMP-2, a key protease in cardiovascular diseases." (PMID 27255968, 2016). "In addition to ROS, nitrogen reactive species (NOS) can cause cardiovascular diseases (CVD) through oxidation of LDL particles and increased release of matrix metalloproteinase-2 (MMP-2) in the coronary effluent." (PMID 27441055, 2016). "Indeed MMP-2, is involved in the pathogenesis of a wide viriety of cardiovascular disorders." (PMID 22713251, 2012). "The gelatinases, MMP-2 and MMP-9, as well as matrilysin (MMP-7), have been the focus of extensive research in various cardiovascular diseases, largely because of their crucial involvement in the regulation of VSMC migration and proliferation." (PMID 39200884, 2024). "MMP2 and MMP9 belong to the most frequently analyzed MMPs in relation to HF syndrome and other cardiovascular diseases." (PMID 35885988, 2022). "Additionally, therapeutic strategies targeting MMP-2 activity, such as the use of specific inhibitors, may offer new avenues for managing and mitigating vascular and cardiac complications in patients with RH and patients with cardiovascular disease as in our prior study." (PMID 40311090, 2025). "In conclusion, we found high expression of DDR2 in atherosclerotic plaques of human and various animal models, and DDR2 in VSMCs was involved with collagen I-induced secretion of MMP-2, suggesting that the clinical role of DDR2 in cardiovascular disease should be elucidated in further experiments." (PMID 34956435, 2021). "To date, evidence has shown that MMP-2 and MMP-9 are the only two genes which epigenetic modification may contribute to the development of cardiovascular disease." (PMID 27295295, 2016). "In spite of some clinical trial reversals, recent studies of non-selective MMP inhibitors and anti-oxidants suggest that MMP-2 remains a compelling pharmacologic target for the treatment of cardiovascular disease." (PMID 23874529, 2013).
adenocarcinoma (24 papers, 2003 to 2024). A common cancer characterized by the presence of malignant glandular cells. "The expressions of MMP-1 and MMP-2 have shown a statistical correlation to the mucinous histological type with signet ring cells when compared to NOS adenocarcinoma." (PMID 32813775, 2020). "When adenocarcinoma A549 cells were exposed to the microgravity environment, MMP-2, MMP-9, TIMP-1, and TIMP-2 showed higher expression in the MG than in the CONT at 24 h." (PMID 31601869, 2019). "The results were comparable: VEGFA and VEGFR2 patterns of expression were similar; VEGFD, FGF2 were significantly downregulated as in lepidic adenocarcinomas and MMP2 was also significantly downregulated." (PMID 29137669, 2017). "Aconitine has effects on inhibiting cell proliferation invasion and metastasis of human adenocarcinoma A549 cell lines through decreasing the expression of MMP-2 and MMP-9 activity." (PMID 29234363, 2017). "If our results show differences with the human adenocarcinomas regarding the expression MMP-2, -7 and -9, the overexpression of MMP-13 is consistent with human tumors." (PMID 26193700, 2015). "The MMP-2 immunoreactive protein was evaluated from primary adenocarcinoma of the breast in 453 cases by using a specific monoclonal antibody in immunohistochemical stainings." (PMID 14520459, 2003). "Furthermore, the MMP-2 concentration was found to be statistically significantly higher in adenocarcinoma patients with the -735CC genotype (x ̄ = 157.69 ng/mL) than in adenocarcinoma patients with the -735CT genotype (x ̄ = 126.37 ng/mL, p = 0.013222)." (PMID 37445754, 2023). "In this study, we demonstrated that the inflammatory cytokine rIL-6 affects the migration and the invasiveness of two human primary adenocarcinoma cells, namely, T88 and T93 cells, and that this effect is well-correlated with the up-regulation of MMP-2 enzyme activity and mRNA expression levels." (PMID 34885656, 2021). "After 24 h on a 3D RPM, the migration-related genes MMP-2, MMP-9, TIMP-1, and TIMP-2 were all upregulated both in a squamous (H1703) and in an adenocarcinoma (A549) cell line." (PMID 37048115, 2023). "In our study, there was a correlation between MMP-2 gene and protein expressions with the mucinous histological type with signet ring cells and NOS adenocarcinoma." (PMID 32813775, 2020). "It has been reported that DDP treatment suppressed the MMP2 and MMP9 protein expressions significantly in human adenocarcinoma cell line A549." (PMID 33329003, 2020). "For example, a soya bean BBI can suppress MMP‐2 and MMP‐9 enzyme activity to inhibit the growth of the two adenocarcinoma cells AGS and HT29." (PMID 32415911, 2020). "For example, CK2 inhibitors decrease cell migration and invasion in human adenocarcinoma and NSCLC cell lines, seemingly through downregulation of MMP-2 transcript expression and activity via the ERK pathway." (PMID 28134850, 2017). "A meta-analysis performed in 2010 demonstrated that high expression of Mmp-2 was marker of poor prognosis in NSCLC and in adenocarcinoma patients." (PMID 26654940, 2016). "K-rasLSL-G12D mice were imaged serially during the development of adenocarcinomas using fluorescence molecular tomography (FMT) and a probe specific for MMP-2, -3, -9 and -13." (PMID 26193700, 2015). "Single nucleotide polymorphisms (SNPs) at four TIMP (TIMP1-4) and three MMP genes (MMP2, MMP7 and MMP9) were genotyped in DNA samples from a prospective cohort of patients with primary adenocarcinoma of the GEJ admitted to the British Columbia Cancer Agency." (PMID 23527119, 2013). "In the -735CT genotype, we found the highest MMP-2 level in the non-smoking control (x ̄ = 237.00 ng/mL), and the lowest in adenocarcinoma patients (x ̄ = 126.37 ng/mL)." (PMID 37445754, 2023). "Similarly, MMP-2 occurred with mucinous and NOS adenocarcinoma histological types (p = 0.01 and fold change of 2.17) and peritumoral inflammatory infiltrate (p = 0.04 and fold change of −1.2)." (PMID 32813775, 2020).
adenocarcinoma (continued). "Moreover, mRNA expression VEGFD, FGF2 MMP2, NRP1 and NRP2 was decreased in lepidic adenocarcinomas when compared to the normal lungs." (PMID 29137669, 2017). "Considering other SASP factors secreted by irradiated MSCs, particularly MMP2, high mRNA expression levels did not correlate to worse OS for all NSCLC patients, but when considering adenocarcinoma patients only." (PMID 39011489, 2024). "On the contrary, we observed decreased mRNA expression of VEGFD, FGF2 and MMP2 and the absence of VEGFR2 proteins in human lepidic adenocarcinomas." (PMID 29137669, 2017). "Interestingly, mRNA expression of the MMP2, NRP1 and NRP2 genes was lower (but not significant) in lepidic-type adenocarcinomas as compared to normal tissues from the same patients." (PMID 29137669, 2017).
kidney disease (23 papers, 2009 to 2024). "Inhibition of Mmp2 activity results in disparate outcomes depending on the phase of kidney disease studied and on the underlying cause." (PMID 26673451, 2015). "Plasma MMP-2,-3 and -9 provide information that is complementary to conventional risk factors and baseline eGFR for kidney disease progression." (PMID 23922934, 2013). "Further, we demonstrated, within the context of transgenic renal proximal tubule expression of MMP-2, that expression of this gene was sufficient to recapitulate all of the features of progressive human renal disease, including loss of nephron mass, interstitial fibrosis, and inflammation." (PMID 26379248, 2015). "MMP-2 activity exhibits distinct patterns across the stages of kidney function impairment, with varying roles in the progression of renal disease." (PMID 39769454, 2024). "MMP-2 leads to structural alterations at the level of the tubular basement membrane and can generate all of the common features of kidney disease, including glomerulosclerosis, tubular atrophy, and interstitial fibrosis." (PMID 33419373, 2020). "Early combination therapy with inhibitors of Mmp2, Mmp3 and Mmp9 significantly delayed the onset of proteinuria, while treatment after onset of proteinuria accelerated renal disease." (PMID 26673451, 2015). "Till now, to our best knowledge, the relationship between plasma MMP-2, -3 and -9 levels and kidney disease progression is unclear in CAD patients." (PMID 23922934, 2013). "A majority of studies in patients with kidney diseases as well as animal models hereof demonstrate that the renal content of MMP‐2 and MMP‐9 are increased." (PMID 24744860, 2013). "This study prospectively demonstrated that baseline MMP-2, -3 and -9 levels were the independent predictors for faster eGFR decline and subsequent kidney disease progression." (PMID 23922934, 2013). "MMP-2 dysregulation in CKD has been linked to increased levels of fibrotic markers such as collagen and α-SMA, highlighting its role as a potential therapeutic target for fibrosis in renal diseases." (PMID 39769454, 2024). "For example, MMP-9 and MMP-2 have been elevated in various kidney disease models and humans, and urinary TIMP-1 has already been proposed as a marker of kidney function in patients after kidney transplantation and also its expressions have been increased in patients with CKD." (PMID 35205098, 2022). "Since the downregulation of PTGER3 and upregulation of MMP-2 are protective for renal diseases, the agonists of PTGER3 (including iloprost and treprostinil) and inhibitor of MMP-2 (like captopril) might be inapplicable for the treatment of DN." (PMID 33435900, 2021). "Until recently, studies on the pathophysiologic roles of MMP-2 in renal disease have focused on the secreted form of MMP-2 (denoted in this report as full length MMP-2, FL-MMP-2), with an emphasis on modulation of the extracellular matrix and tubular basement membrane." (PMID 26379248, 2015). "The resultant increased AP-2/DNA binding activity leads to increased synthesis of MMP-2 and increased metalloproteinase activity, which may contribute to the protective effect of female gender on renal disease progression." (PMID 24926343, 2014). "Circulating MMP-2, -3 and -9 are independently associated with kidney disease progression in non-diabetic CAD patients and add incremental predictive power to conventional risk factors." (PMID 23922934, 2013). "In the present study, the most compelling finding is that elevated MMP-2,-3 and -9 plasma levels are prognostic biomarkers for kidney disease progression independent of the conventional risk factors." (PMID 23922934, 2013). "We also provided novel evidence that combining the MMP-2, -3 and -9 significantly adds the predictive value of conventional risk factors for kidney disease progression in a non-diabetic CAD cohort." (PMID 23922934, 2013).
kidney disease (continued). "In summary, circulating MMP-2, -3 and -9 are independently associated with subsequent progression of kidney disease in non-diabetic CAD patients." (PMID 23922934, 2013). "On the other hand, the involvement of MMP-2 and TIMP-2 in kidney disease progression has been demonstrated." (PMID 38610612, 2024). "It has also been reported that MMP-9 plays a role in atherosclerosis development, and both MMP-2 and MMP-9, along with growth factors and cytokines, play roles in the development of proteinuria, tubulointerstitial fibrosis, and kidney disease progression." (PMID 33419373, 2020). "Several reports indicate that MMP-2 and MMP-9, which are expressed in glomerular injury, control extracellular matrix turnover in kidney disease states." (PMID 29461477, 2018). "The results of the ELISA in the present study showed that MMP-2 and -9 and TIMP-1 and -2 were present in the sera from all kidney disease patients analyzed." (PMID 24520285, 2014). "Moreover, previous studies indicate that MMP-2 and MMP-9 are overexpressed in the glomerulus in kidney disease states." (PMID 29461477, 2018).
cardiac disease (22 papers, 2012 to 2024). "ARP-100 was used as MMP-2 specific inhibitor already in other studies on heart disease: in isolated hearts, ARP-100 reduced ischemia-reperfusion injury via protection against junctophilin 2 or SERCA (Sarcoplasmic reticulum calcium ATPase) degradation." (PMID 33400052, 2021). "The novel aspects of MMP-2's action in heart injury have been reviewed by Schulz, the role of MMPs in cardiac diseases has been reviewed by Spinale, and the intracellular actions of MMPs have been reviewed by Hockenbery." (PMID 24455428, 2013). "Investigations into the role of MMP-2 in cardiac disease can be divided into three relatively discrete levels of inquiry." (PMID 23874529, 2013). "MMP-2 plays multifaceted roles in cardiac disease and the current study adds yet another, and unexpected, level of complexity." (PMID 22509276, 2012). "The experimental and clinical evidence supporting a major role for MMP-2 in cardiac disease, is well documented." (PMID 22509276, 2012). "In addition, they showed a positive correlation between abnormal cardiac relaxation and elevated levels of MMP-2, demonstrating the possibility of these gelatinases becoming biomarkers in the development of heart diseases in individuals infected with T. cruzi." (PMID 37587436, 2023). "Modulation of MMP-2 by non-selective or specific inhibitors has the potential to provide new directions for studying the mechanisms underlying various heart diseases, including HF." (PMID 35893744, 2022). "Furthermore, we found a significant correlation between plasma VAP-1 and MMP-2, one of the main mediators of pathologic extracellular matrix remodeling and fibrosis in several cardiac diseases." (PMID 34557529, 2021). "We believe that MMP-2 represents a transition period between clinical forms and that changes in its production may signal initial changes and remodeling of cardiac disease." (PMID 31578449, 2019). "Ongoing proteomic studies of the N-terminal truncated MMP-2 transgenic mice may be expected to provide new mechanistic insights into the pathogenesis of cardiac disease, particularly in the setting of acute or chronic oxidant stress." (PMID 22509276, 2012). "Six candidate genes including LMNA, Zinc Finger Homeobox 3 (ZFHX3), Matrix Metallopeptidase 2 (MMP2), Angiopoietin-Like 5 (ANGPTL5), Myosin Heavy Chain 7B (MYH7B) and Potassium voltage-gated channel subfamily H member 6 (KCNH6) have been previously linked to heart disease." (PMID 24349489, 2013). "Numerous scientific reports confirm that MMP2 and MMP9 have been recognized to play an important role in matrix remodeling in these cardiac disease states." (PMID 35885988, 2022). "Matrix metalloproteinase-2 (MMP-2) has been extensively studied in both experimental models and human cardiac disease and has been a therapeutic target in a limited number of clinical trials." (PMID 31461499, 2019). "Other study indicated that MMP-2 and MMP-9 levels peaks in plasma from patients clinically asymptomatic with an abnormal ECG (an early indicator of cardiac disease) and progressively augmented in patients with advancing Chagas cardiomyopathy." (PMID 29375564, 2017). "Although MMPs are strongly associated with several inflammatory diseases, the data suggested that MMP-2 and MMP-9 plasmatic levels could be used as early biomarkers of cardiac disease." (PMID 29375564, 2017). "The participation of MMP-2 and MMP-9 in several heart diseases has been well established." (PMID 28118356, 2017). "MMP-2 and MMP-9 are known to play key roles in various cardiac disease conditions." (PMID 25822525, 2015). "Additionally, there are reports indicating that the inhibition of MMP-2 and 9 activation may occur through the inhibition of the RhoA/ROCK pathway, but this issue has not yet been widely studied in heart diseases, although metalloproteinases play an important role in their pathomechanism." (PMID 38540212, 2024).